TSPYL2 (TSPY like 2)
Diseases named in the same sentence as TSPYL2 in open-access papers (continued):
Sharing a sentence is not in itself a finding about the gene and the disease.
cancer (continued). "Nevertheless, we noticed that, in MG-63 cells, SRY depletion by siRNA transfection restores the pattern of TSPYL2 accumulation observed in normal and female cancer cells." (PMID 36918555, 2023). "In carcinoma cells, TSPYL2 is an essential component of the repressor element 1 silencing transcription factor (REST) transcription complex." (PMID 30051352, 2019). "Importantly, at least in cancer cells, this TSPYL2 function is sex-specific since expression of the male-specific gene SRY prevents TSPYL2 accumulation in male cancer cells." (PMID 36918555, 2023). "Furthermore, TSPYL2 induces a sex-dependent response to genotoxic stress in cancer cell lines, restricting cellular proliferation after DNA damage specifically in female cells." (PMID 36918555, 2023). "Indeed, E2F1 silencing completely abrogates the induction of TSPYL2 expression in response to etoposide in different normal and cancer male and female cell lines." (PMID 36918555, 2023). "We found data about TSPYL2 gene for 10953 cancer patients, and we identified TSPYL2 mutations in 225 of them (2%), with missense mutations being the most represented (37,3%), followed by amplifications (27,1%), homodeletions (22,7%) and truncating mutations (10,2%)." (PMID 36918555, 2023). "Therefore, TSPYL2 accumulation is required to sustain cell growth arrest in response to DNA damage in female cancer cell lines." (PMID 36918555, 2023). "Conversely, in male cancer cells, TSPYL2 is still ubiquitinated by MDM2 and degraded." (PMID 36918555, 2023). "Finally, we found that TSPYL2 accumulation is required to prevent the proliferation of female cancer cells exposed to DNA damage and that, accordingly, TSPYL2 gene is more frequently mutated in female-specific tumors." (PMID 36918555, 2023). "As we found that TSPYL2 mRNA is upregulated in all the tested cell lines, we hypothesized that after DNA damage the protein may be degraded in male cancer cells." (PMID 36918555, 2023). "Since loss of TSPYL2 accumulation in male cancer cells is not due to reduced transcription, we hypothesized that SRY may regulate TSPYL2 levels indirectly or through a transcription-independent mechanism." (PMID 36918555, 2023). "Conversely, SRY overexpression in the female cancer cell lines U2OS and HeLa and in the male normal ARPE-19 cells is sufficient to reduce the accumulation of TSPYL2 at both 24 and 48 h after etoposide treatment." (PMID 36918555, 2023). "Altogether these data indicate that, after etoposide treatment, TSPYL2 protein accumulates in normal and in female cancer cell lines, but not in male cancer cells, unless they lost the Y chromosome." (PMID 36918555, 2023). "To extend our findings, we investigated TSPYL2 protein levels 24 and 48 h after etoposide treatment in different human non-transformed and cancer cell lines." (PMID 36918555, 2023). "Indeed, some male cancer cell lines showed a reduction of TSPYL2 after etoposide (e.g. A549, DU145, Jurkat and HT1080), while in others (e.g. MG-63 and HCT116) TSPYL2 decreased at 24 h after damage and then accumulated at 48 h." (PMID 36918555, 2023). "After DNA damage, E2F1 promotes TSPYL2 gene expression in cells of both sexes, but the protein accumulates only in female cancer cells, where it is no longer ubiquitinated." (PMID 36918555, 2023). "As TSPYL2 was under-expressed in most cancers and showed negative correlations with UBE2C that were very weak to moderate, we analyzed the RNA–RNA association between TSPYL and UBE2C using RNAup webserver and also RNA–protein interactions using RPISeq." (PMID 31067633, 2019). "Collectively these results suggest that, in unstressed conditions, TSPYL2 is regulated by ubiquitination and proteasome-dependent degradation, while after DNA damage, TSPYL2 is no longer ubiquitinated in female cancer cells but still targeted for degradation in male cancer cell lines." (PMID 36918555, 2023).
cancer (continued). "Finally, we silenced E2F1 in different normal and cancer cell lines of both sexes and no significant changes in TSPYL2 mRNA levels were found in unstressed conditions." (PMID 36918555, 2023). "Like non-transformed cell lines, TSPYL2 levels raised at 24 and 48 h after etoposide treatment in female cancer cells, while on the contrary, a more variable regulation, never leading to the protein accumulation found in normal cells, was detected in male cells." (PMID 36918555, 2023). "It is worthy to note that TSPYL2 showed down-regulation in most of the 27 cancers and also very weak to strong negative correlation with UBE2C in most of these studied cancers." (PMID 31067633, 2019).
neurodevelopmental disorder (2 papers, 2019 to 2024). A behavioral and cognitive disorder with onset during the developmental period that involves impaired or aberrant development of intellectual, motor, or social functions. "Testis-specific protein, Y-encoded-like 2 (TSPYL2) is an X-linked gene in the locus for several neurodevelopmental disorders." (PMID 30051352, 2019). "These functional studies provide evidence for the contribution of TSPYL2 in neurodevelopmental disorders linked to its chromosome location Xp11 in humans." (PMID 30051352, 2019). "TSPYL2 was described in many patients with Xp11.2 microduplications and neurodevelopmental disorders." (PMID 38572415, 2024).
infection (1 paper, 2023). The state of being infected such as from the introduction of a foreign agent such as serum, vaccine, antigenic substance or organism. "Additionally, transwell migration and wound healing assays were conducted to identify the migration ability of HFL1 cells after infection with Lv-Tspyl2." (PMID 37391440, 2023).
TSPYL2 also shares sentences with these, for which no sentence is quoted: melanoma (3 papers); cervical cancer (2); liver cancer (2); lung adenocarcinoma (2); anaplastic large cell lymphoma (1); colon cancer (1); cutaneous T-cell lymphoma (1); degenerative diseases (1); FG syndrome 4 (1); hepatosplenic T-cell lymphoma (1); Intellectual disability (1); learning disability (1); leukemia (1); lung squamous cell carcinoma (1); male infertility (1); microcephaly (1); mycosis fungoides (1); myeloproliferative neoplasm (1); non-small cell lung carcinoma (1); Nystagmus (1); pulmonary fibrosis (1); schizophrenia (1); squamous cell carcinoma (1); triple-negative breast carcinoma (1).